ERBB2 (erb-b2 receptor tyrosine kinase 2)
Diseases named in the same sentence as ERBB2 in open-access papers (continued):
Sharing a sentence is not in itself a finding about the gene and the disease.
breast cancer (continued). "We have reported that RCAS carrying an activated version of ErbB2 (RCAS-caErbB2) induces mammary tumors with a median latency of 6 months in MMTV-tva mice that express tva from the MMTV promoter, which is active in the great majority of cells in the mammary epithelium." (PMID 24265712, 2013). "Relevance to the human disease is underlined by the findings that PGC-1α expression is positively correlated with that of the glutamine pathway in ERBB2+ breast cancer patients, and that high expression of the glutamine pathway is associated with shorter survival time." (PMID 24304688, 2013). "Additional tyrosine kinase inhibitors (TKIs) targeting various cellular signaling pathways have entered the clinic since imatinib mesylate was approved by the FDA in 2001, including inhibitors targeting ERBB2 in breast cancer and the related RTK, EGFR, in lung adenocarcinomas." (PMID 23630663, 2013). "There is a general concern that erbB2+ breast cancer cell lines are difficult to form spontaneous xenografts in athymic nu/nu mice, and it is not known whether the BT474-HR20 cells would maintain their trastuzumab-resistant phenotype in vivo." (PMID 24215614, 2013). "In addition, CD151-silenced MCF-10A breast cancer cells expressing ErbB2 also showed reduced β4 integrin phosphorylation at S1424 in response to EGF stimulation." (PMID 23613949, 2013). "According to different reports, 15 to 30% of breast cancers are driven by overexpression of ERBB2." (PMID 23593223, 2013). "We hypothesized that the anti-erbB3 Ab MM-121 can overcome trastuzumab resistance and enhance the efficacy of trastuzumab against erbB2+ breast cancer." (PMID 24215614, 2013). "Taken together, our data indicate that the erbB3 blocking Ab MM-121 significantly enhances trastuzumab-induced growth inhibition in two erbB2+ breast cancer cell lines and exhibits potential to overcome trastuzumab resistance mainly through inactivation of the erbB3/PI-3K/Akt signaling." (PMID 24215614, 2013). "It has been reported that FLOT1 was a regulator of ErbB2 in breast cancer." (PMID 23840303, 2013). "In human breast cancer, several works refer to ERBB2 mRNA overexpression in a low percentage of samples, and some recent works have also observed low levels of ERBB2 mRNA, suggesting the occurrence of ERBB2 mRNA underexpression in HBC." (PMID 24386251, 2013). "A similar dependency on glutamine was observed with human ERBB2+ breast cancer cell lines." (PMID 24304688, 2013). "We may assume that immune response may play a specific role in ERBB2+ breast cancer, relating to serum CK." (PMID 23614022, 2013). "Interestingly, previous studies have suggested that elevated flotillin-2 expression in gastric cancers correlates with ErbB2 levels, and flotillins are required to stabilize ErbB2 in the plasma membrane in SKBR3 breast cancer cells." (PMID 24304721, 2013). "These breast cancers are divided into 6–10 subtypes that are highly heterogeneous both histologically and by gene expression profiling: luminal A, luminal B, ERBB2/HER2, normal breast-like, basal-like and triple-negative (TN)." (PMID 23307470, 2013). "In addition to inducing paclitaxel resistance, the erbB2/erbB3/PI-3 K/Akt signaling also results in resistance to hormonal therapy and other chemotherapy in breast cancer treatment." (PMID 24168763, 2013). "For instance, Hexokinase2 (HK2), an enzyme catalyzing the first committed step of glucose metabolism, has recently been shown to be required for tumor initiation and maintenance by using mouse models of KRas-driven lung cancer and ErbB2-driven breast cancer with Hk2 conditional knockout." (PMID 24318446, 2013). "To explore the possibility, we developed a stochastic model of human breast cancer by breeding STK11fl/f mice (FVB) with mice genetically engineered to express activated Neu/HER2-MMTV-Cre (FVB) under the endogenous Erbb2 promoter, referred to as NIC mice, to generate STK11−/−/NIC mice." (PMID 23451056, 2013).
breast cancer (continued). "The reduced levels of miR-125b in breast cancer cells suggests that both ERBB2 and EPOR could become up-regulated and actively cooperate to increase cell proliferation and reduce the apoptotic rate in cancer cells." (PMID 24165569, 2013). "Finally, we report a significant correlation between MBP-1, HDAC1 and ERBB2 protein expression in primary breast carcinomas." (PMID 23421821, 2013). "On the basis of these observations, we hypothesized a direct functional link between MBP-1 and the ERBB2 gene in human breast carcinomas." (PMID 23421821, 2013). "To extend our results to a different experimental model, we took advantage of the human BT-474.m1 breast cancer cell line which displays moderate levels of ER and PR and overexpresses the receptor tyrosine kinase ErbB-2, and which forms tumors in female nude mice." (PMID 22583478, 2012). "Here we demonstrate using two well-characterized transgenic mouse models of ErbB2 breast cancer that while the presence of functional FAK confers a proliferative advantage to ErbB2 tumour cells, metastatic ErbB2 mammary tumours can be generated in the complete absence of FAK expression." (PMID 22373082, 2012). "The roles of HRG and ErbBs in breast cancer, particularly ErbB-2, are well acknowledged." (PMID 22583478, 2012). "Furthermore, knock-in of a catalytically inactive form of p110β blocked tumor development in an ERBB2-GEMM for breast cancer." (PMID 22666248, 2012). "To directly evaluate the role of FAK in mammary tumour progression, we have used a conditional FAK mouse model and mouse mammary tumour virus (MMTV)-driven Cre recombinase strain to inactivate FAK in the mammary epithelium of a transgenic mouse model of ErbB2 breast cancer." (PMID 22373082, 2012). "While significant progress has been made in understanding the role of ErbB2 in breast cancer initiation and progression, the overwhelming resistance to trastuzumab therapy suggests that additional signaling pathways exist that circumvent ErbB2 antibody-mediated blockade." (PMID 22279592, 2012). "ERBB2 amplification and PIK3CA mutation were validated as biomarkers for sensitivity to the single-agent phosphoinositide 3-kinase (PIK3) inhibitor, GDC-0941, in breast cancer models." (PMID 23056620, 2012). "Hence the observed MRS signature provides a basis for the potential use of MRS as a preclinical and clinical biomarker tool for investigating the antitumour activity of HSP90 inhibitors, particularly in the context of NEU/HER2/ERBB2-driven breast cancer." (PMID 22621282, 2012). "In this way, ErbB2 plays a key role in orchestrating an aggressive breast cancer phenotype." (PMID 22279592, 2012). "Recent clinical experience indicates that HSP90 inhibitors are showing therapeutic activity in settings where they deplete sensitive HSP90 clients in tumour types that are addicted to those clients, with ERBB2-positive, trastuzumab-refractory breast cancer providing the best example." (PMID 22621282, 2012). "Several of the genes involved are also in signalling pathways relevant to breast cancer: ERBB2, NRIP1 and BCAS3 are involved in estrogen receptor function and APPBP2 with androgen receptor; while TAOK1 and SKAP1 are involved in MAPK signalling and DEPDC6/DEPTOR regulates mTOR signalling." (PMID 23260012, 2012). "Moreover, cyclin E overexpression has been recently demonstrated to confer trastuzumab resistance in ErbB-2-overexpressing breast cancer." (PMID 22583478, 2012). "For example, although only 20–25% of human breast cancers fall under the ErbB2 positive subtype, more than 45% of human non-invasive breast carcinomas can possess amplified and overexpressed ErbB2 suggesting that ErbB2 overexpression is more frequently associated with non-invasive disease." (PMID 22529912, 2012). "Subsequent studies are now underway to test whether PADI2 plays a functional role in HER2/ERBB2 driven breast cancers, potentially by functioning as an inflammatory mediator." (PMID 23110523, 2012).
breast cancer (continued). "Our data suggest that regulation of the ErbB2/EphrinB1 complex may mediate signals important in breast cancer." (PMID 22279592, 2012). "Combined therapy of anthracycline derivatives and antibodies against erbB2 (i.e., trastuzumab, Herceptin) is clinically effective with objective tumor regressions and lower rates of both recurrence and mortality of breast cancer patients relatively resistant to tamoxifen." (PMID 22970387, 2012). "Supporting our finding in the heart, HSF1 protein levels and activation were shown to be induced by ErbB2 over-expression in a breast cancer cell line, while the mechanism of this ErbB2 connection to HSF1 is still unknown." (PMID 22912742, 2012). "In contrast to the parental MMTV-activated ErbB2 strain and mice harboring one conditional FAK allele, in which mammary tumours occurred with an average onset of 200 days, animals carrying both FAK alleles developed mammary tumours with an average delayed onset of 232 days." (PMID 22373082, 2012). "In addition, cyclin D1 is a critical downstream target of ErbB2-, Ras- and β-catenin- induced breast cancers, and is sufficient for the induction of mammary tumors when targeted to the mammary gland of mice." (PMID 22382486, 2012). "In breast cancers, the ErbB2 over-expression correlates with estrogen independence." (PMID 23133437, 2012). "It therefore represents a good model of ERBB2-amplified breast cancer in the clinic." (PMID 22621282, 2012). "HuR binding has been shown to enhance the stability of mRNAs involved in proliferation, while also playing a role in breast cancer, as cytoplasmic accumulation of HuR promotes tamoxifen resistance in BT-474 cells and the stability of HER2/ERBB2 transcripts in SK-BR-3 cells." (PMID 23110523, 2012). "They found that this improved the prediction of ERBB2 status and relapse in breast cancer." (PMID 22615549, 2012). "Thus, genes specifically upregulated in the presence of progestin in cells expressing SUMO-deficient PR are among the same genes highly over-expressed (top 5% to 10%) in ERBB2-positive breast cancers (shaded rows)." (PMID 22697792, 2012). "To strengthen the hypothesis that PADI2 is primarily expressed in luminal breast cancer cell lines and is coexpressed with HER2/ERBB2, we next investigated PADI2 mRNA levels by querying RNA-seq datasets collected from 57 breast cancer cell lines." (PMID 23110523, 2012). "HER2/erbB2 expression in breast cancer is one of the best known examples of this paradigm with high levels of expression indicating poor prognosis and at the same time favorable response to antibody therapy with anti-HER2 antibody treatment, e.g., with trastuzumab." (PMID 23267434, 2012). "We also confirmed that TetO-driven responder transgenes are active in ErbB2-induced mammary tumors." (PMID 22952764, 2012). "Further studies focused on identifying additional components of the ErbB2/EphrinB1 complex and the downstream pathways they regulate may identify additional targets for therapeutic intervention in breast cancer and other solid tumors." (PMID 22279592, 2012). "Until recently, breast cancer was considered as a single disease with variable phenotype and expression of hormone receptors (HR; estrogen receptor, ER, and progesterone receptor, PR) and ERBB2 tyrosine kinase receptor." (PMID 22082486, 2012). "Previous expression profiling studies have further expanded the concept of clinical heterogeneity and identified five major subtypes of breast cancer: basal epithelial-like, ErbB2-overexpressing, normal breast epithelial-like and two luminal (luminal A and B) subtypes." (PMID 22514728, 2012). "Furthermore, we have shown that CL-316243 treatment in female MKR+/+ mice, caused a significant decrease in the growth rate of both PyVmT and Neu/ErbB2 cell-mediated mammary tumors." (PMID 22226054, 2012).
breast cancer (continued). "Moreover, recent studies have indicated that FAK and the related kinase Pyk2 are expressed in ErbB2-positive breast cancer and contribute to the proliferative and invasive potential of breast cancer cell lines." (PMID 22373082, 2012). "The two genes with particular significance for breast cancer are HER-2/neu (erbB2) and cyclin D1." (PMID 22701509, 2012). "Heregulin, a ligand of HER receptors and more specifically of ErbB3 and ErbB4, which is essential for ErbB2 phosphorylation in response to heregulin, is involved in the progression of different types of human cancers and induces the spread of breast cancer cells in vivo." (PMID 22952755, 2012). "We found that in the nucleus of breast cancer cells, ErbB-2 assembles a transcriptional complex in which it functions as a coactivator of the signal transducer and activator of transcription 3 (Stat3) to promote the expression of cyclin D1, another gene known to induce breast cancer proliferation." (PMID 22356700, 2012). "Then PIK3CA mutation status could serve as a new independent prognostic tool when selecting targeted therapies for patients with ERBB2+ breast cancer." (PMID 22330809, 2012). "ErbB3 has been identified as a key partner for ErbB2, with this receptor heterodimer being identified as an oncogenic unit in breast cancer cells, whilst overexpression of ErbB4 has also been shown to promote growth of human breast cancer cells." (PMID 21396094, 2011). "Moreover, high ErbB-2 expression in tumour-initiating cells of ErbB-2-positive breast cancer cell lines coincides with high Notch-1 expression and activity." (PMID 21847123, 2011). "ErbB2+ mammary tumors progress slowly and give rise to spontaneous metastases." (PMID 24212954, 2011). "In light of the importance of ERBB2 in breast cancer, HB4a and HB4aC5.2, the parental and the ERBB2 overexpressing cell lines, respectively, have been used to investigate quantitative transcriptional alterations in mammary cells mediated by ERBB2 overexpression." (PMID 21731642, 2011). "Similar preclinical findings have also been reported for the pure anti-ER fulvestrant, and recent clinical studies examining cotargeting ER and EGFR and/or ErbB2 signalling pathways have reported improved response to a range of endocrine therapies in breast cancer patients." (PMID 21396094, 2011). "The ErbB-2 proto-oncogene is amplified, overexpressed, and/or hyperactive in 15–25% of patients with breast cancers, such as the ‘HER-2 positive subtype’, which is oestrogen receptor α (ERα) and progesterone receptor (PR) negative, or a subset of the ‘luminal B subtype’, which is ERα/PR positive." (PMID 21847123, 2011). "This approach was shown to be suitable for structural, quantitative, and qualitative assessment of complex transcriptomes and revealed new events mediated by ERBB2 overexpression, in addition to potential molecular targets for breast cancer that are driven by this oncogene." (PMID 21731642, 2011). "Electroporation with DNA plasmids coding for the extracellular and transmembrane domain of the rat (RRT plasmid) or human (HuHuT plasmid) ErbB2 protein elicits a protective response against both rat and human ErbB2+ transplantable mammary tumors in wild-type mice." (PMID 24212954, 2011). "Similarly, in breast cancer patients with ERBB2 (also named HER-2/NEU) overexpression, the monoclonal antibody trastuzumab and the small molecule inhibitor lapatinib are effective." (PMID 21379385, 2011). "Assessment of P2X5 expression using microarray data from 264 human breast cancer samples classified as luminal (A/B), ERBB2+ or basal, indicated that P2X5 is significantly upregulated in the basal subset of clinical breast cancer samples compared to all other subtypes." (PMID 21850275, 2011). "However, there is a high rate of intrinsic resistance to trastuzumab monotherapy among patients with ErbB2-positive breast cancer, ranging from 66% to 88%." (PMID 21457548, 2011).
breast cancer (continued). "Supporting this hypothesis, a recent study has revealed that PAX2 negatively regulates the expression of a well-established pro-invasion and pro-metastastic gene, ERBB2, in estradiol-treated luminal breast cancer cell lines." (PMID 22168360, 2011). "Irreversible ERBB2 inhibitors may offer alternative treatment options for breast cancer and other solid tumor patients harbouring lapatinib resistance mutations." (PMID 22046346, 2011). "Amplification/overexpression of HER2 [human epidermal growth factor receptor, a.k.a., c-ErbB-2, (ERBB2)] is an important cause of sporadic breast cancer that occurs in approximately 30% of breast cancer." (PMID 21422497, 2011). "Molecular apocrine breast cancer constitutes approximately 50% of ER-tumors and is characterized by a steroid response gene signature that includes androgen receptor (AR) and a high frequency of ErbB2 overexpression." (PMID 21457548, 2011). "Our findings, along with evidence from the literature, indicate that Notch could be an important target in trastuzumab-resistant, ErbB-2-positive breast cancer." (PMID 21847123, 2011). "BT474 breast cancer cells contain ErbB-2 gene amplifications and are sensitive to lapatinib." (PMID 21847123, 2011). "By downregulating ERBB2 expression in luminal breast cancer cells, estradiol could negatively regulate their invasiveness; this question, however, had not been directly examined to this day." (PMID 22168360, 2011). "Furthermore, USC cell lines expressed 10-fold higher erbB2 levels than erbB2-positive ovarian and breast cancer cell lines by flowcytometry." (PMID 21876697, 2011). "ErbB2 (HER2) is an oncogene that leads to the development of mammary tumours in mice." (PMID 21576761, 2011). "One possible mechanism was recently identified by Gijsen and colleagues, who reported that blockade of Akt can activate ADAM17 (ADAM metallopeptidase domain 17) in erbB2-overexpressing breast cancer cells, leading to release of heregulins, which can act in an autocrine manner to activate erbB3." (PMID 21939528, 2011). "Furthermore mAb 4C5 was shown to inhibit the extracellular interaction between HSP90 and the growth factor receptor ErbB-2 in MDA-MB-453 breast cancer cells, leading to impaired downstream signalling and reduced cancer cell motility and invasion." (PMID 21912649, 2011). "Finally, Erb-hcAb is active in vitro and in vivo against some Trastuzumab-resistant, ErbB2-positive breast cancer cell lines." (PMID 21559015, 2011). "Other known breast cancer gene target such as ERBB2, E2F1 and MTDH are in the global driver list." (PMID 21806811, 2011). "Additionally, a role in ERBB2-related oncogenesis was proposed for CRIP1 since upregulation of CRIP1 was recorded in ERBB2-overexpressing carcinomas of the breast which generally follow an aggressive course." (PMID 22202598, 2011). "In human ErbB2 tolerant mice, while HuRT is clearly the most effective in hampering the growth of transplantable tumors expressing the human ErbB2 ortholog, it was equally effective as RHuT in halting human ErbB2+ autochthonous mammary carcinomas." (PMID 24212954, 2011). "When the ability of the recombinant fusion protein to bind to ErbB2-positive cells was analysed by ELISA assays, Erb-hcAb-RNase was found to fully retain the specificity and the affinity of the parental compact antibody for mammary carcinoma ErbB2-overexpressing SKBR3 cells." (PMID 21559015, 2011). "Although gene expression profiling has identified an ERBB2 molecular subtype of breast cancer, it is clear that HER2+ tumors reside in all molecular subtypes and represent a genomically and biologically heterogeneous group, needed to be further characterized in large sample sets." (PMID 20459607, 2010). "Our survey indicates that up to 1 in 4 Asian patients with breast cancer potentially could benefit from ErbB2-targeted treatment." (PMID 20715159, 2010).